Y_RNA (Y RNA )
Gene: Miscellaneous RNA gene on chromosome 18 (56,753,226 to 56,753,326, reverse strand). Ensembl gene ENSG00000206865.
Homologues: Orthologues: chimpanzee Y_RNA (100% identical), macaque Y_RNA (96% identical). Paralogues in human: Y_RNA (94% identical), RNY3 (93% identical), Y_RNA (93% identical), Y_RNA (92% identical), Y_RNA (91% identical), RNY3P1 (90% identical), Y_RNA (90% identical), Y_RNA (89% identical), RNY3P16 (88% identical), RNY3P5 (88% identical), Y_RNA (88% identical), RNY3P14 (87% identical), and 98 more.